PNLIP (pancreatic lipase)
Diseases named in the same sentence as PNLIP in open-access papers (continued):
Sharing a sentence is not in itself a finding about the gene and the disease.
Obesity (continued). "It was suggested that these compounds might be of further research value as potential pancreatic lipase inhibitor candidates in the management of obesity and the treatment of related metabolic diseases." (PMID 39330274, 2024). "Furthermore, polyphenols can inhibit the lipogenic pathway and pro-obesity enzymes like pancreatic lipase, which lowers the synthesis and storage of fat." (PMID 38397458, 2024). "Thus, inhibiting pancreatic lipase (PL) and reducing lipid absorption are promising approaches for treating obesity." (PMID 39539624, 2024). "Inhibiting pancreatic lipase is one of the proven strategies for the treatment of obesity." (PMID 38473839, 2024). "In addition to other approaches, a key objective in obesity treatment is to identify inhibitors of pancreatic lipase that can effectively diminish the breakdown and absorption of nutrients." (PMID 38298460, 2024). "In addition, inhibiting the action of pancreatic lipase is another mechanism through which flavonoids exhibit their anti-obesity property." (PMID 37627544, 2023). "Consequently, inhibiting the activities of α-glucosidase and pancreatic lipase has been identified as an effective approach for managing diabetes and obesity." (PMID 37627496, 2023). "Due to the high prevalence of T2D and obesity, various therapeutic approaches have been attempted for their management, including the inhibition of key enzymes such as α-glucosidase and α-amylase and pancreatic lipase." (PMID 37850338, 2023). "Derrone is also an active compound isolated from C. tricuspidata and inhibits pancreatic lipase, thereby suggesting that derrone may be a beneficial candidate for treating obesity." (PMID 37108428, 2023). "Therefore, the empirical anti-obesity effects of Pu’er tea were proposed to be a consequence of blocking fat absorption from diets by inhibiting pancreatic lipase activity in the small intestine." (PMID 37175375, 2023). "Human pancreatic lipase (hPL), a crucial digestive enzyme responsible for the digestion of dietary lipids in humans, has been validated as an important therapeutic target for preventing and treating obesity." (PMID 36832040, 2023). "Therefore, pancreatic lipase is targeted for the development of anti‐obesity agents (Wan‐Loy & Siew‐Moi, 2016)." (PMID 36655073, 2023). "Human pancreatic lipase (hPL) is a crucial digestive enzyme responsible for the digestion of dietary lipids in humans, and inhibition of hPL is effective in reducing triglyceride intake, thereby preventing and treating obesity." (PMID 36832049, 2023). "Our results suggest that ABE might act as an anti-obesity agent by inhibiting pancreatic lipase-mediated fat absorption, at least in part." (PMID 37836509, 2023). "On the other hand, the inhibition of pancreatic lipase decreases the digestion of triglycerides from the food which leads to monoacylglycerols and free fatty acid reduction in the intestinal lumen, which is important in some disease treatments (i.e., obesity)." (PMID 37107232, 2023). "The mechanisms through which polyphenols can inhibit obesity include inhibiting digestive enzymes (mainly alpha-glucosidase, pancreatic lipase, fatty acid synthase, and alpha-amylase), stimulating energy expenditure, suppressing appetite, regulating lipid synthesis, and modulation of gut microbiota." (PMID 36829976, 2023). "Therefore, an essential target for the treatment of obesity includes the development of pancreatic lipase inhibitors." (PMID 36829976, 2023). "Besides, they can act on the most diverse proteins, such as tyrosine phosphatase 1B, AMP-activated protein kinase, interleukin 6 and chemokine ligand 2 and pancreatic lipase, that are proteins involved in the metabolism of both diseases, obesity, and DM." (PMID 37058011, 2023). "These in vitro and in vivo findings suggest that ABE might act as an anti-obesity agent by inhibiting pancreatic lipase-mediated lipid absorption, at least in part." (PMID 37836509, 2023).
Obesity (continued). "Hence, the investigation of pancreatic lipase inhibitors can reveal new agents that would help combat obesity." (PMID 37999391, 2023). "PNLIP and FTO with its associated genes were identified as candidate genes for targeting obesity." (PMID 37808366, 2023). "In turn, obesity and lipid absorption are controlled by pancreatic lipase inhibitors." (PMID 35566071, 2022). "Thus, the inhibition of pancreatic lipase can effectively reduce triglyceride absorption, helping to prevent the development of obesity." (PMID 37431048, 2022). "Therefore, obesity is closely related to lipase activity in humans, and the human body degrades and digests fat taken from food through pancreatic lipase." (PMID 36185652, 2022). "In recent years, increasingly more medicinal herbs have been reported to show inhibitory activities against pancreatic lipase, and discovery of lipase inhibitors among herbal medicines may provide potential alternatives for the treatment of obesity." (PMID 36235143, 2022). "Pancreatic lipase (PL), a key digestive enzyme responsible for the hydrolysis of dietary triglycerides in the gastrointestinal tract, has gained considerable attention as an important anti-obesity target." (PMID 35284458, 2022). "In particular, we demonstrated that free linoleic acid and oleic acid were effective inhibitors of pancreatic lipase and modulators of fat digestion and absorption, and justified their potential use as regulators of energy intake in the management of overweight and obesity." (PMID 35956860, 2022). "One of the most important drug targets of obesity is pancreatic lipase (PL)." (PMID 36296516, 2022). "Previous reports showed that GpS could inhibit pancreatic lipase activity and possibly possess anti‐obesity effect." (PMID 35282005, 2022). "Therefore, previous reports on antihyperlipidemic activity of natural products were mostly targeted on pancreatic lipase inhibition and anti-obesity agents." (PMID 36195907, 2022). "Digestive enzymes such α-amylase (AA), α-glucosidase (AG) and pancreatic lipase (PL), play an important role in the metabolism of carbohydrates and lipids, being attractive therapeutic targets for the treatment of type 2 diabetes and obesity." (PMID 35630761, 2022). "Therefore, it is advisable to eat foods rich in lipase inhibitors, especially pancreatic lipase, which contributes to the inhibition of the development of obesity." (PMID 37431048, 2022). "The synthetized peptides exhibited in vitro antioxidant activity through radical scavenging, ACE inhibitory activity, anti-diabetic effects through inhibition of α-amylase, α-glucosidase, and DPP-IV, and/or obesity modulatory ability by inhibition of pancreatic lipase." (PMID 36358473, 2022). "Therefore, it is necessary to find more natural sources of PNLIP inhibitors, i.e., phenolic acids or polyphenols, contained in plant extracts and study their prospect to be implemented in anti-obesity medications." (PMID 36232503, 2022). "Therefore, the inhibition of pancreatic lipase activity is considered to be one of the most important therapies for preventing obesity." (PMID 35408540, 2022). "The highest inhibition of the tested enzymes was noted for the fruit skin and pulp of biotype Si5 (17.0 and 23.7 mg/mL against α-amylase and α-glucosidase, respectively), whereas obesity was most effectively controlled by the fruit skin and pulp of biotype Si4 (69.0 mg/mL against pancreatic lipase)." (PMID 35566071, 2022). "Interestingly, in this study, among these flavonoids, hesperidin, the most dominant flavonoid in ponkan peel extract, showed the highest pancreatic lipase inhibition activities, suggesting its promising application in managing obesity." (PMID 35204122, 2022). "Thus, the enzymes, including pancreatic lipase (PL), involved in lipid metabolism are potential therapeutic targets for obesity." (PMID 35464030, 2022).
Obesity (continued). "However, phenolic compounds at 7 and 14 mg doses of GAE also inhibited pancreatic lipase in vitro and in vivo; that is, they can have anti-obesity properties." (PMID 35458674, 2022). "Inhibiting pancreatic lipase activity is considered one of the treatment strategies for obesity." (PMID 35282005, 2022). "Pancreatic lipase (PL) is a well-known key target for the prevention and treatment of obesity." (PMID 35100926, 2022). "This review discussed the combat against obesity and reduction of weight using medicinal plants, which is accomplishable through control of appetite, inhibition of pancreatic lipase activity, enhancement of thermogenesis and lipid metabolism as well as increasing of satiety." (PMID 34211580, 2021). "The authors suggested that the administration of PCM could be a different prospective anti-obesity agent for decreasing fat absorption via inhibition of pancreatic lipase." (PMID 34579162, 2021). "On the other hand, significant decreases of the obesity parameters were observed in the OB/OR group in comparison to the OB group, showing that orlistat is a potent gastro-pancreatic lipase drug that is capable of reducing the body weight after six weeks of the therapeutic period." (PMID 33562069, 2021). "Moreover, catechins from green tea have previously been demonstrated to have antiobesity effects through various mechanisms of action, such as the inhibition of pancreatic lipase, as well as through the regulation of obesity-related genes and proteins." (PMID 33540841, 2021). "Therefore, food ingredients that can inhibit excessive pancreatic lipase activity and the development of obesity and support the dietary therapy of the disease are being sought." (PMID 34959917, 2021). "Pancreatic lipase inhibitors can impact the activity of pancreatic lipase, reduce the hydrolysis and absorption of dietary fat and have a preeminent behavior on the treatment of obesity and prevention of its complications." (PMID 34361800, 2021). "Polyphenol-rich apricot leaf extract (PrALe) showed the most effective anti-obesity action through inhibition of pancreatic lipase, COX-1 and antioxidant capacity, especially the oxygen radical absorbance capacity, which was particularly correlated with polyphenolic compounds." (PMID 34942972, 2021). "Eggplant may have shown protective effects on hyperlipidemia and obesity via the induction of lipoprotein lipase activity and the reduction of pancreatic lipase activity.Eggplant can be useful in the treatment of MetS and its complications." (PMID 34094022, 2021). "Thus, our findings regarding the potential of the roots of the plant to inhibit pancreatic lipase, stimulate lipolysis, and reduce lipid accumulation in adipocytes should increase its potential utility for the treatment and prevention of obesity." (PMID 32235329, 2020). "Many countries have used medicinal plants as dietary supplements for the controlling of body weight and, thus, natural inhibitors of pancreatic lipase could be potential candidates to control obesity." (PMID 32326102, 2020). "The inhibitory activity on pancreatic lipase, a key enzyme for the absorption of dietary fats, has also been taken into account in our study, in order to have some preliminary information about the potential anti-obesity properties of this plant species." (PMID 31936818, 2020). "The lipase inhibitory activity method described here was developed to identify potential anti-obesity properties in milk fermented with different strains of lactic acid bacteria via inhibition of pancreatic lipase and a subsequent decrease in fat digestion and absorption in the gut." (PMID 32775223, 2020). "Diets rich in flavonoids have been related with low obesity rates, which could be related with their potential to inhibit pancreatic lipase, the main enzyme of fat assimilation." (PMID 32298262, 2020).
Obesity (continued). "Pancreatic lipase is the major enzyme that converts ingested triglycerides to fatty acids, and as such decreases fat absorption through pancreatic lipase inhibition and can be useful to treat obesity." (PMID 32326102, 2020). "Suppressing pancreatic lipase activity inhibits hydrolysis of triacylglycerol into glycerol and fatty acids, thus inhibiting liposuction through the small mucous membrane, reducing the amount accumulated in the body to prevent obesity." (PMID 33036193, 2020). "Similarly, the use of Orlistat, an anti-obesity drug that limits fat absorption by inhibition of pancreatic lipase, leads to fat malabsorption." (PMID 31948089, 2020). "Consequently, there are a wide variety of drugs currently available for treating obesity, such as pancreatic lipase inhibitors, thermogenic agents and hunger suppressors." (PMID 30818849, 2019). "Obesity control may be by several mechanisms, one of which being that orlistat prevents fat hydrolysis by acting as a gastric and pancreatic lipase inhibitor (Heck, Yanovski & Calis, 2012; Yanovski & Yanovski, 2014)." (PMID 30923658, 2019). "Molecular docking analysis of twenty two phytoconstituents from Hibiscus rosa-sinensis, against seven targets of obesity like pancreatic lipase, fat and obesity protein (FTO protein), cannabinoid receptor, hormones as ghrelin, leptin and protein as SCH1 and MCH1 is detailed in this data article." (PMID 31193691, 2019). "The extract exhibited pancreatic lipase inhibitory activity and may have potential for use as a food supplement for controlling obesity." (PMID 31579625, 2019). "Mangosteen pericarp extract showed inhibitory activity towards pancreatic lipase and may have potential use for obesity treatment." (PMID 31791316, 2019). "Some plant extracts are known to act as anti-obesity agents and have been screened in in vitro models based on the inhibition of lipid accumulation in 3T3-L1 cells and activity of pancreatic lipase methods and in in vivo high-fat diet-induced obesity rat/mouse models and human models." (PMID 31540021, 2019). "In addition, the peel was characterized by a high concentration of monophosphate nucleotides, free amino acids, and were responsible above all for the strong ability to inhibit pancreatic lipase enzymes contributing to the development of obesity." (PMID 31540276, 2019). "The pancreatic lipase inhibition and the synergism showed the potential activity of M. spicata EO and carvone and that their combinations with standard drugs can be useful for the treatment of obesity and overweight." (PMID 31772594, 2019). "Additionally, the optimized crude extract, as well as a subsequent purified phlorotannin fraction, were further evaluated with regard to their antidiabetic and anti-obesity potential through the inhibition of α-glucosidase, α-amylase and pancreatic lipase." (PMID 30857204, 2019). "Thus, inhibiting the digestion and absorption of dietary fat by suppressing PNLIP expression/activity is one effective way of preventing and treating obesity." (PMID 29538343, 2018). "The anti-obesity effects of oolong tea might be due to its inhibitory effect on pancreatic lipase activity." (PMID 30344295, 2018). "The inhibition of pancreatic lipase, the main enzyme responsible for triglyceride digestion, is a strategy to reduce fat absorption and control weight that may decrease obesity." (PMID 30050651, 2018). "Accordingly, nutritional composition, the content of phytochemical antioxidants and the inhibitory ability of key enzymes with impacts on obesity and diabetes (α-glucosidase and pancreatic lipase) or on arterial pressure (angiotensin-I converting enzyme) were assessed." (PMID 30274353, 2018). "Accordingly, nutritional composition, the content of phytochemical antioxidants, and the inhibitory ability of key enzymes with impacts on obesity and diabetes (α-glucosidase and pancreatic lipase) or on arterial pressure (angiotensin-I converting enzyme), were evaluated." (PMID 30274353, 2018).
Obesity (continued). "However, pancreatic lipase inhibitory effect is one of the most widely studied mechanisms to determine the potential activity of natural products as obesity modulating agents." (PMID 30026782, 2018). "The enzyme inhibition is one of the approaches used to treat obesity due to the fact that 50-70 % of total dietary fat hydrolysis was performed by pancreatic lipase.The mechanism involves inhibition of dietary triglyceride absorption, as this is the main source of excess calories." (PMID 30026782, 2018). "Therefore, it is suggested that under conditions that induce SNS activation—including obesity or chronic metabolic disease—β-blockers would contribute to preventing obesity by suppressing PNLIP expression." (PMID 29538343, 2018). "Therefore, a reduction in fat absorption by the inhibition of pancreatic lipase is suggested to be beneficial for the regulation of obesity." (PMID 28253267, 2017). "Oishi and colleagues evaluated the anti-obesity potential of a saponin fraction from Momordica charantia L., discovering that it was able to inhibit the pancreatic lipase activity, as well as the elevation of the serum neutral fat level after corn oil loading in mice." (PMID 27775618, 2016). "Therefore, the present study aims to investigate the inhibition property on porcine pancreatic lipase in vivo and changes in body weight and serum lipid parameters and visceral fat weight on an experimental model of obesity." (PMID 27529064, 2016). "Algal compounds with inhibitory activity against pancreatic lipase could be useful as anti-obesity agents." (PMID 27941599, 2016). "However, the only approved anti-obesity drug currently available in the market is orlistat, a synthetic inhibitor of pancreatic lipase." (PMID 27941599, 2016). "Therefore, compound C1, as a potent pancreatic lipase inhibitor, demonstrates potential benefits in the regulation of obesity." (PMID 26085282, 2015). "Dietary triglycerides are hydrolyzed by pancreatic lipase to monoglycerides, free fatty acids and other small molecules, which are absorbed in the intestine and then resynthesize triglycerides for the person of food intake leading to obesity ultimately." (PMID 23377020, 2013). "Therefore, in this study, the inhibition of pancreatic lipase, assisted with α-amylase inhibitory activity, was selected as the evaluation criterion of anti-obesity." (PMID 23377020, 2013). "In the search for effective anti-obesity compounds from natural sources, several extracts from plants, and bacterial, fungal, and marine species have been screened in order to find new compounds with pancreatic lipase inhibitory activity." (PMID 24287996, 2013). "Taken together, the inhibition of MGAT2 may be a safer strategy than the inhibition of pancreatic lipase for the treatment of obesity." (PMID 22698140, 2012). "Therefore, the application of pancreatic lipase inhibitor was examined earlier as a treatment for high-fat diet-induced obesity in humans." (PMID 15811191, 2005). "Therefore, inhibiting pancreatic lipase is a strategy to combat obesity." (PMID 41134486, 2025). "Specifically, pancreatic lipase (PL) has been used on numerous occasions, both immobilized and in solution, as an important target for screening compounds that inhibit its activity, which could act as potential anti-obesity drugs." (PMID 41002354, 2025). "Therefore, the pancreatic lipase inhibitory peptide released from HEP in the gut may be one of its potential mechanisms against obesity." (PMID 39942052, 2025). "In addition to its antibacterial activity, flavonoid and polyphenol-rich extracts of C. operculatus are also believed to have clinical applications in preventing obesity and type II diabetes due to their potent inhibitory effects on pancreatic lipase, α-amylase, and α-glucosidase." (PMID 38988368, 2024). "Thus, inhibition of pancreatic lipase is recognized as one of the strategies for managing obesity." (PMID 39328713, 2024).